INSR (insulin receptor)
Diseases named in the same sentence as INSR in open-access papers (continued):
Sharing a sentence is not in itself a finding about the gene and the disease.
Insulin resistance (continued). "Increased ROS levels activate the phosphorylation of the insulin receptor and the insulin receptor substrate and decrease the level of the FoxO1 transcriptional factor, which eventually results in insulin resistance." (PMID 30717446, 2019). "In order to better elucidate the role of insulin receptor in DM insulin resistance, we have analysed its expression in muscle samples at RNA and protein levels." (PMID 30901379, 2019). "MG53 by acting as an E3 ligase and through a direct interaction with the insulin receptor and insulin receptor substrate (IRS1) triggers receptor degradation leading to insulin resistance." (PMID 31520263, 2019). "Impaired INSR activities lead to insulin resistance, the key factor in the pathology of metabolic disorders including type 2 diabetes mellitus (T2DM)." (PMID 31658625, 2019). "Overall, these studies suggest a clear correlation between insulin receptor signaling and insulin resistance in the development of AD." (PMID 31143098, 2019). "These serine kinases can alleviate the activation of IRS1, resulting in the impairment of insulin receptor-mediated signaling and the occurrence of insulin resistance." (PMID 31861309, 2019). "Insulin receptor translocation to the nuclei is however a new pathway to enhance our understanding of insulin signaling and insulin resistance." (PMID 31686269, 2019). "In this regard, previous data showed that tissue-specific knockout of the insulin receptor in adipose tissue (FIRKO mice) protects the animal from diet-induced insulin resistance." (PMID 30832230, 2019). "On the other hand, insulin resistance can distort intracellular activities of INSR, which enters a vicious cycle accelerating the development of metabolic diseases." (PMID 31658625, 2019). "An increase in the mitochondrial ROS generation from a nutrient-rich environment induces cellular stress pathways resulting in insulin resistance by interrupting insulin receptor signal transduction." (PMID 31068904, 2019). "Recently we showed that IRTKS is an adaptor of insulin receptor that modulates the insulin-receptor substrate (IRS)–PI3K–AKT signaling pathway via regulation of the phosphorylation of IR and IRS, whilst IRTKS deficiency causes insulin resistance in mice." (PMID 31212584, 2019). "Fascinatingly, it also interacts with the intracellular domain of the insulin receptor (IR) and is involved in the pathogenesis of insulin-resistance when abnormally phosphorylated." (PMID 31551928, 2019). "Alteration of INSR recycling can lead to insulin resistance and consequently result in hyperinsulinemia and metabolic disorders such as obesity and T2DM." (PMID 31658625, 2019). "These proinflammatory markers, as well as CRP, are suggested to induce insulin resistance and gluconeogenesis, subsequent hyperglycemia, and attenuate insulin signaling and sensitivity through insulin receptor substrate phosphorylation." (PMID 31143476, 2019). "We studied the role of antioxidants in the regulation of insulin resistance using the tamoxifen-inducible fat-specific insulin receptor knockout (iFIRKO) mouse model, which allowed us to analyse the antioxidant’s effect in a time-resolved manner." (PMID 31309261, 2019). "The role of INSR activities and trafficking in insulin resistance pathogenesis has been largely ignored." (PMID 31658625, 2019). "Alteration of these activities will lead to an imbalance of INSR availability, which can further develop into insulin resistance." (PMID 31658625, 2019). "Specifically, IL-6 is able to induce insulin resistance in both liver and adipocytes through reduction of phosphorylation of the insulin receptor substrate (IRS), or by transcription inhibition of the IRS." (PMID 31370223, 2019). "Concurrently, induction of HO-1 provides protection against insulin resistance as seen by increased insulin receptor phosphorylation." (PMID 30057822, 2018).
Insulin resistance (continued). "The association of insulin resistance with obesity and T2DM and the fact that insulin receptor signaling is mediated by tyrosine (Tyr) phosphorylation have generated great interest in the homeostasis of tyrosine phosphorylation." (PMID 29786669, 2018). "The molecular mechanism of insulin resistance in these diseases was explained by a reduction in the binding of insulin to its receptor and by a defect in insulin receptor autophosphorylation." (PMID 29972435, 2018). "This study evaluates four well-characterised murine anti-INSR monoclonal antibodies recognising distinct epitopes as surrogate agonists for potential targeted treatment of severe insulin resistance arising from insulin receptoropathies." (PMID 29700562, 2018). "In this experiment, feeding mulberry leaf water solution (80 mg/kg) to diabetic mice significantly reduced fasting blood glucose (FBG) and increased serum insulin levels, resulting in reduced insulin resistance and improved insulin receptor sensitivity." (PMID 30131712, 2018). "We measured beta cell function, proliferation and viability in these mice in response to a high-fat/high-sugar diet and induction of acute insulin resistance with the insulin receptor antagonist S961." (PMID 29497784, 2018). "Even though there are some treatment options available for patients with a Type A insulin resistance phenotype—the mildest form of the INSR-related SIR syndromes—general treatment goals, e.g., long-term normalization of HbA1c cannot be achieved in most cases." (PMID 29695048, 2018). "Insulin resistance can be monitored by the decreased phosphorylation of two main substrates of the insulin receptor, IRS1 and IRS2." (PMID 30024933, 2018). "Studies using genetic models of tissue-specific insulin resistance obtained by selectively knocking out insulin receptor genes with Cre-loxP technology have found differing effects on insulin resistance in different tissues during systemic metabolic disease." (PMID 30692925, 2018). "The etiology and clinical presentation of severe insulin resistance is highly variable, with severe insulin receptor (INSR)-related insulin resistance syndromes (SIR) exhibiting a peculiar phenotypical spectrum." (PMID 29695048, 2018). "Supplementation of rat diet with high cholesterol also induced insulin resistance, although elevated insulin receptor autophosphorylation (its activation) was observed in response to insulin." (PMID 29955245, 2018). "Hyperinsulinemia further increases insulin resistance by damaging insulin receptor at cell site including pancreatic beta cells and responsible for reduction in insulin secretion in later stage of type 2 diabetes." (PMID 30072892, 2018). "We found the onset of insulin resistance in the liver of young rats after fructose-rich diet, as evidenced by the decreased activation of the downstream effectors of insulin receptor, IRS1 and Akt." (PMID 29755364, 2018). "It is, therefore, worthwhile to better understand how we can utilize GCPR in relation to the insulin receptor and its relationship with metabolic disease, diabetes, and increased insulin resistance." (PMID 29462993, 2018). "Elevated TNF-α levels induce insulin resistance by down-regulating the tyrosine kinase activity of the insulin receptor and decreasing the expression of GLUT-4 glucose transporters." (PMID 29189992, 2018). "This condition is similar to ‘insulin resistance’, that the impairment of insulin receptor and signaling cascades was found with elevated serum insulin concentration." (PMID 30185439, 2018). "In diabetes, solid experimental evidence shows that fetuin-A binds the β-subunit of the insulin receptor to attenuate insulin signaling, thereby contributing to insulin resistance in type 2 diabetes mellitus (T2DM)." (PMID 30060600, 2018). "In glucose homeostasis, LRP1 has a regulatory action on the insulin receptor (IR) and GLUT4 activation, which has been strongly associated with insulin resistance developed during MetS." (PMID 29914093, 2018).
Insulin resistance (continued). "Insulin resistance is a pathological condition in which the insulin receptor (IR) is insensitive to insulin and signaling pathway cannot be sufficiently activated." (PMID 29513799, 2018). "Oxidative stress can result in insulin resistance by phosphorylating serine residues in insulin receptor, which subsequently inhibits the phosphorylation of the tyrosine residues, and ultimately causes insulin receptors inactivation and insulin resistance." (PMID 31565649, 2018). "Insulin resistance, a hallmark of type 2 DM (T2DM), results from disequilibrium in auto-phosphorylation of the insulin receptor (IR) and tyrosine kinase activity." (PMID 28608833, 2017). "Socs3 has been reported to be highly expressed in the obese liver, and to bind to the insulin receptor, inducing insulin resistance." (PMID 28870184, 2017). "The Ras-ERK insulin pathway is another cascade of insulin receptor activation, which has been less studied in insulin resistance." (PMID 28587267, 2017). "JNK mediates the effect of stress on insulin resistance through inhibitory phosphorylation of insulin receptor substrates." (PMID 29069751, 2017). "In a mouse model of insulin resistance induced by insulin receptor antagonist S961, hepatic and WAT overexpression of betatrophin was observed." (PMID 28702052, 2017). "The elevated levels of these inflammatory cytokines impaired insulin receptor action and thereby prevented downstream signaling pathways, exacerbating insulin resistance in HepG2 cells." (PMID 29096724, 2017). "Recent evidence suggests a strong link between atherosclerosis and insulin resistance due to impaired insulin receptor (IR) signaling." (PMID 28752048, 2017). "There is evidence in animal models that oral advanced AGEs induce insulin resistance by altering insulin receptor signaling leading to impaired glucose-uptake." (PMID 28426788, 2017). "They reported that ANGPTL8−/− mice with insulin resistance induced by a high-fat diet or insulin receptor antagonist S961 had normal beta cell expansion." (PMID 28702052, 2017). "Defects in insulin receptor signaling pathway are observed in most of the systemic insulin resistance." (PMID 29085434, 2017). "More in detail, Sestrins increase AMPK activation, consequentially inhibiting mTORC1 activity, known to induce insulin resistance through the inhibition insulin receptor substrates and the consequent reduction of phosphoinositide-3-kinase (PI3K)/Akt signaling." (PMID 28529490, 2017). "Supporting the value of targeting caveolins, insulin-resistance in obese and DM mice is reversed by hepatic overexpression of caveolin-3, which substantially enhances InsR signaling." (PMID 29202762, 2017). "Inhibition of the insulin receptor signaling pathway by inflammation or stress is a key mechanism of insulin resistance." (PMID 29085434, 2017). "Recent evidence suggests a strong link between atherosclerosis and insulin resistance, due to impaired insulin receptor (IR) signalling." (PMID 28899902, 2017). "Betatrophin, a liver-derived hormone proposed as a potent stimulator of β cell proliferation, has been found increased in a mouse model of insulin resistance (IR) using the insulin receptor antagonist S9611." (PMID 28717133, 2017). "Targeted knockout of the mouse insulin receptor gene in β cells, which artificially disrupted or inhibited of β cells insulin signaling pathway, resulted in insulin resistance and secretion dysfunction in β cells." (PMID 29240812, 2017). "The most commonly proposed mechanism for the fructose-induced insulin resistance appears to be the diminished ability of insulin to suppress hepatic glucose output and decrease insulin receptor density apparent in skeletal muscle and liver." (PMID 28555043, 2017). "Palmitate induced insulin resistance as indicated by impaired insulin-induced phosphorylation of insulin receptor, Akt, Gsk3β and FoxO1." (PMID 28933767, 2017).
Insulin resistance (continued). "Previous studies showed that insulin resistance in 50% of women with PCOS is related to excessive phosphorylation of serine in insulin receptor by the serine/threonine kinas enzyme." (PMID 29387827, 2017). "More detailed analysis and understanding of the roles of miR-96 in diet-induced insulin resistance can be found in "Induction of miR-96 by dietary saturated fatty acids exacerbates hepatic insulin resistance through the suppression of INSR and IRS-1"." (PMID 29124099, 2017). "Growth hormone elevation induces insulin resistance, hence a subsequent elevation of insulin and the potential for activation of insulin receptor." (PMID 29152592, 2017). "As metformin increases signaling by the insulin receptor, leading to an improvement in insulin resistance and a reduction in circulating insulin levels, it is regularly used as an insulin sensitizer." (PMID 27725832, 2016). "Tiwari and colleagues reported reduced expression of the insulin receptor in the kidneys of insulin-resistant rats; our findings add another parameter leading to decreased IR when compared to “insulin resistance”, the presence of increased insulin levels." (PMID 27434075, 2016). "In fact, the downregulation of HMGA1 protein leads to a reduced insulin receptor (INSR) expression in patients with insulin resistance and type 2 diabetes." (PMID 26895108, 2016). "Nevertheless, metformin has been reported to improve insulin resistance and reduce the dose of exogenous insulin needed to control hyperglycemia in patient with anti-insulin receptor antibodies." (PMID 27142369, 2016). "Insulin resistance is a key driver of type 2 diabetes (T2D) and is characterized by defective insulin receptor (INSR) signalling." (PMID 27577745, 2016). "This splicing modulation should be beneficial for DM1 as it reverts the INSR aberrant splicing towards WT conditions, an event that would also be predicted to reduce insulin resistance in patients." (PMID 26824521, 2016). "Peripheral insulin resistance is then defined by a decrease in insulin-dependent glucose transport at the level of target tissues due to defects at both the insulin receptor and/or postreceptor signaling." (PMID 27725832, 2016). "Acquired anti-insulin receptor antibodies induce severe insulin resistance, called “type B insulin resistance,” which was first reported in 1976." (PMID 27456688, 2016). "Insulin receptor levels at the cell surface are reduced in insulin resistance, for reasons that are not fully understood." (PMID 27577745, 2016). "Tumor necrosis factor (TNF-α), which plays an important role in insulin resistance through inhibition of the tyrosine kinase activity of the insulin receptor, has recently gained attention for its potential value." (PMID 27089331, 2016). "One important example of mis-splicing in DM1 is the increase in exon 11 exclusion of the insulin receptor (INSR), which results in the overproduction of the IR-A splice variant, thereby contributing to insulin resistance in DM1 patients." (PMID 26824521, 2016). "The HMGA1-p was found overexpressed in diabetic patients then causing a significant destabilization of HMGA1 mRNA with consequent loss of INSR expression, which is regulated by HMGA1, then generating the insulin resistance phenotype." (PMID 26895108, 2016). "In the present study, we have used iLIRKO (inducible liver insulin receptor knockout) mice, as a model of severe hepatic insulin resistance and T2DM." (PMID 27562101, 2016). "One of the hallmarks of T2DM is peripheral insulin resistance, in part due to unproductive insulin signaling through the insulin receptor." (PMID 27526875, 2016). "Insulin resistance induced by a high fat diet involves decreased protein levels of insulin signaling pathway factors, such as insulin receptor (IR), phosphoinositide 3-kinase (PI3K), and Akt4,5." (PMID 27508151, 2016).
Insulin resistance (continued). "For diabetes patients with cancer, the development of insulin resistance is reported to be combined with frequent insulin receptor overexpression and increased insulin activity in cancer cells." (PMID 26939025, 2016). "Under the schema of selective insulin resistance, insulin receptor signalling via insulin receptor substrate (IRS)/PI3K/PKB/FoxO1 to suppress gluconeogenesis is dysfunctional, but signalling via SREBP1c is maintained." (PMID 25740151, 2016). "After binding to its receptors, TNFα can lead to insulin resistance via inhibiting insulin receptor (IR) signaling." (PMID 26877773, 2016). "This hormone was identified after the authors injected mice with S961 peptide, an insulin receptor antagonist, generating an insulin resistance mouse model." (PMID 27672665, 2016). "The activation of MAPK proteins in hepatic cells resulted from hyperglycemia and inflammatory stimuli, increased insulin receptor phosphorylation and insulin resistance in mice model of diabetes." (PMID 27942499, 2016). "The activities of insulin signaling pathway were measured by phosphorylation level of insulin receptor as a parameter of insulin resistance." (PMID 28053990, 2016). "Never the less, both studies indicated that there is a significant down-regulation of INSR expression pattern in insulin resistance and T2D samples." (PMID 27602317, 2016). "Inflammatory cytokines produced during lipid overload promotes insulin resistance by inhibiting the pathways downstream of insulin receptor signaling and by perpetuating the inflammatory cascade." (PMID 27684068, 2016). "IL-6 also plays a direct role in insulin resistance by inhibiting insulin receptor signal transduction and insulin action in hepatocytes." (PMID 27213439, 2016). "Nevertheless, the suppressive effect on INSR and ADIPOR1 indicated in this study deserves further research, as decreased expression of mRNA levels for these receptors has been linked to insulin resistance and diabetes in humans and animals." (PMID 27983572, 2016). "For example, TNF-α is an important mediator of insulin resistance in obesity owing to its inhibitory effects on insulin receptor signaling." (PMID 27213439, 2016). "We previously reported that mutant mice harboring a single amino acid substitution in the insulin receptor (InsrP1195L/+ mice) exhibit insulin resistance but normal glucose tolerance." (PMID 26615883, 2015). "SOCS3 induces insulin resistance through increased phosphorylation of the insulin receptor on tyrosine 960, which inhibits the insulin receptor/IRS-1 interaction." (PMID 25874611, 2015). "Obesity causes hypertrophy of adipose tissue that leads to the release of diverse inflammatory cytokines, such as TNF-α and IL-1β, and these increased cytokines lead to insulin resistance through the inhibition of the insulin receptor signaling pathway." (PMID 26569269, 2015). "Insulin resistance is the key feature of type 2 diabetes and is manifested as attenuated insulin receptor (IR) signaling in response to same levels of insulin binding." (PMID 25799496, 2015). "As part of the multisystem involvement, many DM1 patients show insulin resistance due to the aberrant splicing of the insulin receptor (IR) mRNA, which is highly expressed in skeletal muscle." (PMID 26217220, 2015). "Recent reports have shown that accumulated hepatic TGs result in insulin resistance by inhibiting insulin receptor signaling." (PMID 25816097, 2015). "Alternatively, obese women with PCOS possess alterations in insulin receptor expression, with underexpression in metabolic tissues and overexpression in the ovary, resulting in peripheral insulin resistance and excess ovarian androgen production." (PMID 26305227, 2015). "Decreased INSR expression in metabolic tissues is consistent with insulin resistance and provides a potential mechanism for insulin resistance frequently seen in obese women with PCOS." (PMID 26305227, 2015).